LEPR (leptin receptor)
Diseases named in the same sentence as LEPR in open-access papers (continued):
Sharing a sentence is not in itself a finding about the gene and the disease.
tumor (continued). "Here, we evaluated the impact of leptin receptor (ObR) knockdown in affecting BC phenotype and in mediating the interaction between tumor cells and macrophages, the most abundant immune cells within the TME." (PMID 32727138, 2020). "The present study demonstrates the expression of leptin and LepR and their involvement in tumor progression." (PMID 30803210, 2019). "Given the already established role of LEP/LEPR system in growth promotion, it may be assumed to be causally related to carcinogenesis, where its growth effect may go out of control and result in tumorous growths or its hyperactivity may help the tumor to grow faster." (PMID 31592340, 2019). "Leptin secreted into BMA binds leptin receptor on the tumour cells, which induces tumour progression." (PMID 31334678, 2019). "Absence in expression level of leptin receptor correlated with low tumor proliferation rate in 94.1% of the cases, while high proliferation rate associated with 92% of the cases with pronounced expression." (PMID 29682217, 2018). "Leptin activated the downstream Jak2/STAT3 signaling in LepR(+) tumor cells, which led to enhanced proliferation, survival and migration of tumor cells." (PMID 30013512, 2018). "In breast cancer, the expression of leptin receptor is highly upregulated in tumor tissue, particularly in the CSC subpopulation, as driven by the self-renewal associated transcription factors OCT-4 and SOX-2." (PMID 28337221, 2017). "Collectively, this work has shown that LEPR signaling is able to positively impact on several key tumor-promoting phenotypes that are also influenced by other IL-6R-related receptors, such as IL-6R itself and G-CSFR." (PMID 29212170, 2017). "The genomic instability of the miR-34a-high tumor cell line was reflected in high-copy amplicons coding for the oncogenes Yap1, Birc2, Birc3, Dcun1d5 (all on 9A1) or the leptin receptor (4C6)." (PMID 26871287, 2016). "Both of the leptin receptor knockdown lines showed reduced tumor weights in the DIO mice, yet only LRKD2 showed a statistically decreased tumor weight when compared to the parental or the control shRNA Panc02 cell lines grown in the DIO mice." (PMID 25919692, 2015). "Leptin-receptor expression showed a positive correlation with a larger tumor size (≥ 5cm) (P < 0.05)." (PMID 26147886, 2015). "In vivo, depletion of the leptin receptor through shRNA knockdown partially abrogated increased orthotopic tumor growth in obese mice." (PMID 25919692, 2015). "Our IHC results show that leptin-receptor expression decreases in the tumor microenvironment of overweight and obese mice." (PMID 25599228, 2015). "Ob-R, the leptin receptor levels were significantly lower in the tumor tissue than the tissues adjacent to the tumor (p = 0.01)." (PMID 26431176, 2015). "It is shown that leptin receptor is a characteristic feature of Tumor initiating stem cells (TISCs) and participates in the regulation of core pluripotency-associated transcription factors, Oct4 and Nanog." (PMID 26359358, 2015). "The combination of tumour grade and HER2 status showed the most significant ORs of (9.8 and 4.1) to have LEPR expression higher in lymph nodes than in tumours." (PMID 25482303, 2014). "A wide variety of immune, normal epithelial and epithelial-derived tumor cell types including colon epithelial cells express the leptin receptor, which mediates leptin's biological effects." (PMID 24465801, 2014). "The use of a different leptin receptor antagonist peptide in a mouse model using MDA-MB231 cells also resulted in a significant reduction of tumor growth." (PMID 24202338, 2013). "A number of studies indicate that LEPR are overexpressed in many tumor tissues and that there are leptin-responsive tumors including mammary carcinomas, pancreatic, esophageal, gastric, and colon tumors." (PMID 23819063, 2013).
tumor (continued). "Animal studies demonstrate that subcutaneous injection of leptin receptor antagonist peptide delayed the development and slowed the growth of breast cancer tumors, suggesting the involvement of leptin in tumor latency and growth." (PMID 24176089, 2013). "Others did not observe any significant differences for the fasting serum leptin levels in patients according to pTNM staging although a role for the leptin receptor is discussed in relation with the tumor immune response." (PMID 21254741, 2010). "It promotes tumor-promoting functions through binding with the canonical leptin receptor (ObR)." (PMID 40649751, 2025). "Notably, LEPR overexpression has been implicated in the progression of GBM, where it promotes tumor growth and endothelial-cell-dependent angiogenesis." (PMID 40806198, 2025). "Many LEPR antagonists exhibit anti-cancer activity in various cancer subtypes and models, though few studies have specifically examined the effect of LEPR inhibitors on tumor angiogenesis." (PMID 39439572, 2024). "All patients in the study group had positive leptin receptor expression in the tumor tissue." (PMID 36981858, 2023). "The expression of LEP and LEPR did not showed association with menopausal status, histological type, tumor size, tumor grade and metastasis status (P > 0.05), as well as the expression of ER, PR (P > 0.05)." (PMID 36941557, 2023). "Levels of serum leptin receptor were shown to be elevated for all FMC tumor subtypes." (PMID 37626804, 2023). "Previous study analyzed the expression of LEP, long isoform of LEPR and short isoform of LEPR in 322 primary BC tissues and found that the long isoform of LEPR and the short isoform of LEPR were expressed in all tumor tissues and LEP was expressed in 318 samples." (PMID 36941557, 2023). "Moreover, peptide analogues located at the binding site of leptin and leptin receptor (ObR) can selectively inhibit the interaction between leptin and leptin receptor, thereby inhibiting tumor occurrence and metastasis." (PMID 37666813, 2023). "Regarding clinical actionability, according to whole‐exome sequencing of hepatitis C virus (HCV)‐infected cirrhotic tissues, LEPR is one of the most common mutations in cirrhotic tissues, including tumor and nontumor tissues." (PMID 36052737, 2022). "The importance of LEPR in regulating PI3K–AKT–mTOR in SCC-CSCs extended to in vivo tumours." (PMID 36450983, 2022). "The CRC microenvironment is related to LEP and LEPR expression, with significantly higher leptin levels in patients, indicating the potential of this molecular autocrine/paracrine signaling loop to interfere with tumor progression processes." (PMID 35563103, 2022). "Similarly, the expression of LEPR in tumor tissue was also remarkably elevated compared with that in normal tissues (p < 0.001)." (PMID 35115495, 2022). "The absence of leptin receptor expression was found to be associated with a low tumor proliferation index in 94.1% of cases." (PMID 33799880, 2021). "In this study, serum leptin and leptin receptor (ObR) levels were investigated in 58 cats with mammary carcinoma and compared with those of healthy animals, as were the expression levels of leptin and ObR in tumor tissues." (PMID 33644151, 2021). "Leptin signaling through the leptin receptor also activates angiogenesis and might be an important mediator between the tumor and its microenvironment." (PMID 34210055, 2021). "Additionally, leptin secreted by BMAs reacts with LepR on tumor cells and contributes to tumor progression." (PMID 32674405, 2020). "In addition, blocking leptin signaling using a full-length leptin receptor (ObR) antagonist also reduced mammosphere formation indicating a potential therapeutic target to block stromal-tumor interactions driving breast CSC-mediated disease progression." (PMID 33339340, 2020). "The identification of altered levels of leptin and leptin receptor proteins in tumour tissues may lead to targeted treatment for cancer." (PMID 32802842, 2020).
tumor (continued). "Mechanisms underlying LEPR downregulation and its association with increased tumour progression are not yet understood." (PMID 33167358, 2020). "In this way, KHDRBS1 may play a role in amplifying the response of bone metastasis to leptin, which would underscore the relevance of the leptin/LEPR system in tumour progression." (PMID 33213024, 2020). "The expression of leptin receptor across grades of the tumor has been tabulated." (PMID 30803210, 2019). "Second, leptin/LepR pathway could promote the oncogenesis, proliferation and colonization of tumor cells in the bone marrow niche." (PMID 30013512, 2018). "The increased L/A ratio and wide distribution of LepR could create a suitable niche for tumor growth in the bone marrow." (PMID 30013512, 2018). "In addition, the mediator of leptin-leptin receptor in triggering tumor proliferation was identified." (PMID 29682217, 2018). "Strikingly, the D-KO mice displayed a full protection against the development of large tumors and a reduced total tumor burden compared to IL-6Rα single knockouts, which grants LEPR signaling a compensating tumor-promoting effect in DEN induced HCC development." (PMID 30224299, 2018). "Moreover, for the first time, it was found that leptin upregulates Notch in PC, and the specific inhibition of leptin receptor delays tumor onset, decreases tumor growth and PCSC populations." (PMID 27999190, 2017). "PC cells secreted leptin and expressed the leptin receptor, OB-R, which indicates a leptin autocrine/paracrine signaling loop could also affect tumor progression." (PMID 27999190, 2017). "Expression of the leptin receptor was correlated with expression of ER and tumor size." (PMID 27338371, 2016). "Our results suggest that leptin/leptin receptor signaling may represent a potential therapeutic target that can block the stromal-tumor interactions driving BCSC-mediated disease progression." (PMID 26556856, 2016). "We could also show that leptin activates potent oncogenic pathways depending on JAK2/STAT3, AKT and ERK1/2 in the tumor cell line that carried a high-copy amplicon on the locus of the leptin receptor." (PMID 26871287, 2016). "Leptin receptor knockdown Panc02 cells were used to determine whether the in vivo pancreatic orthotopic tumor growth increase observed in obese mice was due to increased leptin signaling in DIO mice." (PMID 25919692, 2015). "Future studies should focus on finding a correlation between cancer activation pathways, leptin receptor tissue expression, and serum leptin levels, which could then be used as a tumor marker in the clinical setting." (PMID 24867470, 2014). "Based on these considerations, the VDR may be regarded as a mitochondria-targeting tumor facilitator, similar to the role proposed for the leptin receptor, the signaling of which supports cancer cell metabolism by suppressing mitochondrial respiration." (PMID 25546457, 2014). "Furthermore, in ER-negative patients, SK1 and LEPR-Long expression was significantly higher in metastatic LNs than in primary tumours or LNs from ER-positive patients." (PMID 25482303, 2014). "Leptin signaling plays an important role in tumor cell growth and survival that may be mediated through a set of responses of LEPR-positive tumor cells including cancer stem cells." (PMID 23819063, 2013). "Cumulatively, the aminoacid change in this SNP may influence the signal for receptor intracellular recycling or degradation, modulating the availability of membrane-bound leptin receptor in tumor cells." (PMID 22792137, 2012). "Therefore, the authors hypothesized that higher levels of leptin receptor on a tumor, and thus, greater ability for leptin to act upon cancer cells, are associated with FMC tumor growth and survival." (PMID 37626804, 2023).
tumor (continued). "Moreover, this study also found that the expression of LEP and LEPR were balanced when stratified by patients’ age, menopausal status, tumor size, tumor pathological classification, distant metastasis and the expression of ER and PR, which was consistent with previous study." (PMID 36941557, 2023). "Furthermore, the absence of leptin receptor expression in histopathological samples from CRC patients has been associated with decreased tumor proliferation and metastasis and, if associated with obesity, chemotherapy resistance." (PMID 36361914, 2022). "Finally, we investigated ZNF32 and LEPR expression in clinical tumor specimens from CRC patients." (PMID 35115495, 2022). "In summary, LepR may dominate in many kinds of tumor tissues." (PMID 30013512, 2018). "Use of leptin receptor deficient mice in the murine KrasG12D genetic model system may provide more information on these aspects of tumor development in the absence of leptin." (PMID 25919692, 2015). "Therefore the overall impact of 2.17-mAlb on tumor growth was determined not only by the direct effects of LepR antagonist on tumor cells and/or other cells supporting tumor growth, but also by other systemic factors such as insulin metabolism that are regulated by leptin." (PMID 24587106, 2014). "LEPR immunofluorescence corroborated its location in invasive mouse SCCs, and was also found human SCC tumours and xenografts." (PMID 36450983, 2022). "And interfering with LEPR expression significantly inhibited CRC cells colon formation and tumor formation." (PMID 35115495, 2022). "Overall, these results suggested that LEPR identifies a subpopulation of TGFβ-signalling, oncogenic-RAS-driven SCC progenitors endowed with heightened stemness and tumour-initiating ability." (PMID 36450983, 2022). "Elevated LepR mRNA and FGFR1 mRNA were positively correlated in primary breast tissue (R = 0.51), in areas adjacent to the tumor (R = 0.62), and to a lesser extent in normal tissue (R = 0.46)." (PMID 33019728, 2020). "LEPR was high level in HCC tissues and there was a significant correlation between the expression of LEPR and micro-vessel density in tumor tissue." (PMID 33369452, 2020). "The link between the IGF1R‐PTPN1 proteins is known: literature data indicate a crucial role of PTPN1 as a tumour suppressor, able to negatively regulate multiple pathways of cell growth directly through IGF1R and IR, or indirectly through leptin receptor GHR." (PMID 29577582, 2018). "We identified that high tumor expression of LEP and LEPR separately showed a trend toward poor survival." (PMID 29212170, 2017). "The network includes genes that are cancer promoters and tumor suppressors such as FYN HSPA8, YWHAZ, LEPR and TGFBR2, IRF2, EP3000 respectively." (PMID 18811983, 2008). "The leptin receptor antagonist peptide allo-ACA can specifically bind to OBR, inhibit the expression of downstream signal channels and cyclins induced by OBR activation, and inhibit leptin-stimulated tumor cell proliferation." (PMID 37691919, 2023). "In contrast, the study of Tutino in Italy revealed patients with higher tumor stages had increased leptin receptor serum levels, although this difference was not statistically significant." (PMID 37942199, 2023). "The expression of leptin receptors, including LEPR (1.61 vs. 1.13, and p = 0.046), LEPROT (1.42 vs. 1.04, and p = 0.002), LEPROTL1 (1.31 vs.1.10, and p = 0.036), were elevated in CP tumor tissue compared to normal brain tissue." (PMID 37509115, 2023). "Furthermore, we confirmed that knocked out the LEPR gene in SW480-lv-ZNF32 and pCRC1-lv-ZNF32, the CD133 and Ki-67 positive cells were decreased, and the proportion of apoptosis cells was increased in tumor tissues." (PMID 35115495, 2022).
tumor (continued). "The so-called inflammatory CAFs (iCAFs) that express ALDH1A1, KLF4, LEPR, and CXCL12 were distributed across the areas that contain both tumor and immune-stromal cells, whereas the myofibroblast CAFs were enriched only in the tumor cell-enriched area." (PMID 36376874, 2022). "Additionally, the knockdown of LEPR in ER-positive MCF-7 and in triple-negative MDA-MB-231 BC cells (ObR sh) was demonstrated to hamper macrophage recruitment in the tumor microenvironment (TME) and influence immune response." (PMID 36291602, 2022). "In this study, we evaluated whether the leptin/LEPR/KHDRBS1 axis, reported in the cellular model as relevant to tumour progression, could be expressed in bone metastatic tissue in vivo." (PMID 33213024, 2020). "Without estrogen signaling, it is attractive to speculate that tumor progression may be driven by other signaling factors such as either FGFR1 signaling and/or LepR signaling." (PMID 33019728, 2020). "Cancer cells release leptin and express leptin receptor (LEPR), which suggests the potential leptin autocrine/paracrine signaling loop could affect tumor progression." (PMID 29682217, 2018). "The increased leptin could bind to LepR and activate Jak2/STAT3 signaling in BMSCs, thus forming more BMAs and creating a positive feedback for tumor cells." (PMID 30013512, 2018). "The secretion of leptin by adipocytes activates the STAT3 signaling in CSCs and induces the expression of OCT-4 and SOX-2, in turn stimulating the expression of leptin receptor, which maintains a self-reinforcing signaling cascade to expand the CSC population and promote tumor growth." (PMID 28337221, 2017). "The expression profiling of 115 chromatin regulators in tumor and adjacent non-tumor tissues from HFD-induced and leptin receptor-deficient (db/db) obese mice identified the overexpression of HDAC8 in tumor tissues, which was confirmed in NAFLD-associated HCC patient samples." (PMID 32443737, 2020). "Furthermore, the polymorphisms rs7799039 in LEP and rs1137101 in LEPR increased the risk for developing DTC, although they did not appear to correlate with tumour aggressiveness." (PMID 25810718, 2015). "In a colorectal cancer xenograft model, LEPR inhibition (via Allo-aca) blocks NILCO-induced expression of VEGFR1/2, although this did not affect the overall tumor growth rate in mice." (PMID 39439572, 2024).